IL21 (interleukin 21)
Diseases named in the same sentence as IL21 in open-access papers (continued):
Sharing a sentence is not in itself a finding about the gene and the disease.
common variable immunodeficiency (3 papers, 2020 to 2021). "No mutations in genes associated with EBV disease, common variable immunodeficiency or pertaining to the IL-21 signaling pathway (including hypermorphic IL-21 mutations) were found." (PMID 33228556, 2020).
endothelial dysfunction (3 papers, 2022 to 2024). In vascular diseases, endothelial dysfunction is a systemic pathological state of the endothelium (the inner lining of blood vessels) and can be broadly defined as an imbalance between vasodilating and vasoconstricting substances produced by (or acting on) the endothelium. "Moreover, the neutralization of IL-21 results in decreased blood pressure, alleviation of vascular inflammation, and improvement in endothelial dysfunction." (PMID 38045685, 2023). "The absence of IL-21 can prevent Ang II-induced vascular remodeling and endothelial dysfunction." (PMID 38791032, 2024).
eosinophilia (3 papers, 2018 to 2024). "However, mixed results have been reported regarding the impact of IL-21 in asthmatic mice; for example, studies suggest that IL-21 either promotes airway eosinophilia and type 2 immunity, or inhibits IgE production and decreases eosinophil recruitment into the airways." (PMID 34867940, 2021).
esophageal squamous cell carcinoma (3 papers, 2010 to 2025). Esophageal squamous cell carcinoma (ESCC) is a type of esophageal carcinoma (EC) that can affect any part of the esophagus, but is usually located in the upper or middle third. "In this study, we evaluated whether IL-21 could improve the impairment of ADCC in patients with oesophageal squamous cell carcinoma (ESCC), as IL-21 was reported to have the ability to activate NK cells." (PMID 20029417, 2010).
gingivitis (3 papers, 2021 to 2023). A disorder involving inflammation of the gums; may affect surrounding and supporting structures of the teeth. "In patients with gingivitis, levels of IL-1β, IL-6, IL-7, IL-13, IL-17, IL-21 and MIP-3α in gingival crevicular fluid in the Sg group were lower in comparison with the Dg group." (PMID 33417619, 2021). "IL-1β, IL-6, IL-7, IL-13, IL-17, IL-21 and MIP-3α in GCF of T2DM patients with gingivitis were significantly downregulated by statins treatment." (PMID 33417619, 2021).
Hyperglycemia (3 papers, 2018 to 2026). An increased concentration of glucose in the blood. "Therefore, the elevated plasma IL-21 levels do not appear to be associated with the extent of beta-cell destruction, hyperglycemia itself, or with underlying inflammation in T1D patients in the cohort studied." (PMID 37415982, 2023).
Kawasaki disease (3 papers, 2014 to 2018). A rare inflammatory disease characterized by an acute febrile, systemic, self-limiting, medium-vessel vasculitis primarily affecting children. "In summary, significant variations were identified in the percentages of cTfh-cell subsets and the level of serum IL-21 in Kawasaki disease." (PMID 30587125, 2018). "To investigate the role of cTfh cells in the development of Kawasaki disease (KD), we analyzed the distinct subpopulations of cTfh cells and serum IL-21 levels in different phases of KD." (PMID 30587125, 2018).
malnutrition (3 papers, 2021 to 2025). Inadequate nutrition resulting from poor diet, malabsorption, or abnormal nutrient distribution. "Protein levels of IL-17A (p < 0.05), IL-21 (p < 0.05), and IL-22 (p < 0.05) were significantly increased in the LP and LPi mice due to malnutrition." (PMID 34207946, 2021). "Furthermore, beyond disrupting metabolic and endocrine functions in diabetic patients, malnutrition also profoundly modifies immune-related cytokine expression, including interleukin-2 (IL-2), interleukin-8 (IL-8), and interleukin-21 (IL-21)." (PMID 40977986, 2025). "Increased levels of duodenal IL-17A, IL-21, IL-22, CXCL5 due to malnutrition—together with decreased levels of TNFα, IL-12, TGFβ and CXCL10 and elevated levels of IgA due to infection—revealed that the duodenum was sensitive to both variables and suggested local inflammation in malnourished animals." (PMID 34207946, 2021).
MALT lymphoma (3 papers, 2020 to 2022). An indolent, extranodal type of non-Hodgkin lymphoma composed of small B-lymphocytes (centrocyte-like cells). "Recent transcriptomic analyses of salivary gland biopsy specimens from SD patients identified Tfh gene signature and increased IL21 in specimens with ectopic GC and increased IL-21-producing Tfh in those with mucosa-associated lymphoid tissue lymphomas." (PMID 33916486, 2021). "They found that CXCR5–CD4+PD1hiICOS+Foxp3– Tph cells co-expressed IL-21 and interferon-γ, but low IL-17 in parotid MALT-lymphoma." (PMID 35755031, 2022).
myasthenia gravis (3 papers, 2020 to 2024). Myasthenia gravis (MG) is a rare, clinically heterogeneous, autoimmune disorder of the neuromuscular junction characterized by fatigable weakness of voluntary muscles. "Also, in a cohort of patients with recently diagnosed myasthenia gravis, glucocorticoid treatment reduced the IL-21 levels and IL21 mRNA in PBMC." (PMID 39124778, 2024).
myositis (3 papers, 2021 to 2025). "Increased IL-1α, IL-21, LIF, and PlGF-1 levels were significantly associated with the incidence of myositis, and the serum levels of six cytokines (BTLA, GM-CSF, IL-4, PD-1, PD-L1 and TIM-3) were higher in patients who developed a rash." (PMID 36159840, 2022). "Increased IL-1α, IL-21, LIF, and PIGF-1 levels were significantly associated with myositis incidence, while the serum levels of six cytokines (BTLA, GM-CSF, IL-4, PD-1, PD-L1 and TIM-3) were higher in patients with rash." (PMID 36159840, 2022). "A recent study showed that in patients with myositis, IL-21 expressing CCR7lo PD-1hi efficient cTfh cells significantly increased, and the frequencies of these cells had a correlation with the disease progression." (PMID 33465845, 2021).
polyp (3 papers, 2015 to 2017). A usually exophytic mass attached to the underlying tissue by a broad base or a thin stalk. "Studies in CRS have reported increased levels of IL-21 mRNA and protein using ELISA in polyp tissues and peripheral blood." (PMID 29311948, 2017). "IL-21-expressing CD8+ T cells in polyp tissues expressed higher CXCR5, PD-1, and ICOS levels than cells in control tissues and showed significantly higher T-bet and Bcl-6 expression levels compared with IL-21−CD8+ T cells." (PMID 27468819, 2016). "Our previous studies showed that polyp tissues contained significantly higher IL-21 production compared with control mucosa tissues and that IL-21 level positively correlated with polyp size and surgical recurrence of NP patients." (PMID 27468819, 2016). "To identify the phenotypic characteristics of IL-21-expressing CD8+ T cells in polyp tissues, we analyzed the expression of memory phenotype markers." (PMID 27468819, 2016). "Some of the IL-21-producing CD8+ T cells in polyp tissues co-expressed IFN-γ, CXCR5, PD-1, ICOS, T-bet and Bcl-6, which display the T follicular helper (Tfh) cell functionality." (PMID 27468819, 2016). "The transcription factor analysis showed that IL-21-expressing CD8+ T cells in polyp tissues expressed higher levels of Bcl-6 and T-bet than did IL-21−CD8+ T cells, and polyp CD8+ T cells were capable of promoting IgG generation by purified polyp B cells." (PMID 27468819, 2016). "To evaluate the cell subsets of IL-21-expressing CD8+ T cells in polyp tissues, we compared the cytokine expression by CD8+ T cells in polyp and control sinonasal tissues." (PMID 27468819, 2016). "In the present study, we found that CD8+ T cells from polyp tissues produced high levels of IL-21 as well." (PMID 27468819, 2016). "Moreover, the percentage of IL-21+CD8+ T cells in polyp tissues was positively correlated with endoscopic and CT scan scores in NP patients." (PMID 27468819, 2016). "Moreover, the percentage of CXCR5+IL-21+, ICOS+IL-21+ and PD-1+IL-21+ cells in CD8+ T cells was higher in polyp tissues than in control sinonasal tissues (P < 0.01)." (PMID 27468819, 2016). "Moreover, an immunofluorescence assay confirmed the presence of IL-21-expressing CD8+ T cells in polyp tissues." (PMID 27468819, 2016). "Moreover, IL-21 promoted the differentiation of plasma cells and the production of Igs and was positively related to polyp size and recurrence after surgery." (PMID 26239551, 2015). "Moreover, the IL-21-expressing CD8+ T cells in polyp tissues were positively correlated with the endoscopic and CT scores in NP patients (P < 0.01), suggesting that CD8+ T cells may play a critical role in the formation of NPs." (PMID 27468819, 2016). "In the present study, our results showed that polyp CD8+ T cells produced high IL-21 levels, and the percentage of IL-21+CD8+ T cells in polyp tissues was positively correlated with the endoscopic and CT scan scores of NP patients." (PMID 27468819, 2016). "Our results demonstrated that most IL-21+CD8+ T cells expressed high CD45RO levels but minimal CD62L and CCR7 levels, exhibiting an effector memory phenotype in polyp tissues." (PMID 27468819, 2016). "The percentage of IFN-γ+ cells amongst the IL-21+CD8+ T cells was significantly higher than the percentage of IL-17A+ and IL-4+ cells in the polyp tissues (P < 0.001)." (PMID 27468819, 2016). "The expression of CXCR5, PD-1 and ICOS on CD8+ T cells in polyp tissues was significantly increased compared with control tissues (P < 0.01), and some IL-21-expressing CD8+ T cells were found to co-express CXCR5, ICOS and PD-1 in polyp tissues." (PMID 27468819, 2016). "The majority of IL-21-producing CD8+ T cells from polyp tissues co-expressed IFN-γ, but not IL-17 or IL-4, indicating that Tc1 cells were the main IL-21-producing CD8+ T cell subset in polyp tissues." (PMID 27468819, 2016).
polyp (continued). "To evaluate whether IL-12 was able to increase IL-21 production by CD8+ T cells, we stimulated lymphocytes from polyp tissues or purified CD8+ T cellsfrom PBMCs of NPs patients with IL-12." (PMID 27468819, 2016). "We found that the expression of IL-21 by CD8+ T cells, in polyp tissues of both atopic and non-atopic patients, was significantly increased compared with control sinonasal tissues." (PMID 27468819, 2016).
preeclampsia (3 papers, 2020 to 2025). Preeclampsia is a hypertensive disorder of pregnancy that is characterized by new-onset hypertension with proteinuria presenting after 20 weeks of gestation, and depending on mild or severe forms may initially present with severe headache, visual disturbances, and hyperreflexia. "During the third trimester, the concentration of placental small EVs and levels of two EV-encapsulated cytokines (IL21 and IL-22) were significantly higher in the preeclampsia patients." (PMID 36237987, 2022). "In preeclampsia, the frequency of circulating Tfh cells and the level of IL-21 and IL-6 were higher compared to healthy pregnant women; this is probably associated with the production of disorder-specific autoantibodies." (PMID 32265904, 2020). "In light of the obtained data, the increased percentage of Th17 lymphocytes characterized by the simultaneous expression of IL-21 and IL-22 appears to be of particular importance, as it may constitute a potential immunological predictive marker for gestational hypertension." (PMID 41156157, 2025). "In the case of Th17 lymphocytes simultaneously expressing IL-21 and IL-22, a positive correlation was observed with maternal age (rho = 0.335; p = 0.0109), suggesting that this type of immune response may be more strongly represented in older pregnant women with gestational hypertension." (PMID 41156157, 2025). "During the second trimester, the total small EVs concentration and levels of three EV-encapsulated cytokines (IL-21, IL-22, and TGF-β) were significantly higher in the preeclampsia patients than in the healthy controls." (PMID 36237987, 2022). "Therefore, the aim of our study was to assess the population of Treg (CD4+CD25+FoxP3+) and Th17 lymphocytes, as well as the intracellular expression of IL-17A, IL-17F, IL-21, and IL-22 in women with PIH (including preeclampsia)." (PMID 41156157, 2025).
pulmonary tuberculosis (3 papers, 2014 to 2022). A bacterial infection that affects the lungs and is caused by Mycobacterium tuberculosis. "IL-2 and IL-21 have been shown to be important to host resistance in animal models and regulation of these cytokines has been demonstrated in human pulmonary TB." (PMID 32373129, 2020).
relapsing-remitting multiple sclerosis (3 papers, 2017). The most common clinical variant of multiple sclerosis, characterized by recurrent acute exacerbations of neurologic dysfunction followed by partial or complete recovery. "For instance, we have recently evidenced that CD28-mediated upregulation of pro-inflammatory cytokines (i.e., IL-8, IL-6, IL-21, and IL-17A) was higher in human primary T lymphocytes from relapsing-remitting multiple sclerosis patients (RRMS) compared with HD." (PMID 28491063, 2017). "Overexpressed IRF4 in naive CD4+ T cells derived from relapsing remitting multiple sclerosis patients significantly increased their ability to secrete IL-17A, IL-17F, IL-21, and IL-22." (PMID 28808358, 2017).
renal fibrosis (3 papers, 2023 to 2024). A final common manifestation of a wide variety of chronic kidney diseases characterized by glomerulosclerosis and tubulointerstitial fibrosis. "However, the underlying mechanisms of IL-21 and renal fibrosis remain poorly defined." (PMID 37628716, 2023). "In the IgAN, recent studies showed that Tfh cells in tertiary lymphoid structure contributed to the renal fibrosis by IL-21 and the renal progression by activating B cells cell–cell interactions." (PMID 39136821, 2024). "Of note, TFH cells’ attenuation by the ICOS neutralization antibody resulted in the inhibition of TLS formation, IL-21 expression, and renal fibrosis in vivo." (PMID 37628716, 2023). "In conclusion, our data show that T follicular helper cells contribute to TLS formation and renal fibrosis by IL-21." (PMID 37628716, 2023). "Our results together suggested that TFH cells contribute to TLS formation and renal fibrosis by IL-21." (PMID 37628716, 2023). "To evaluate the influence of IL-21 as a pro-fibrotic cytokine on renal fibrosis, we stimulated NRK-49F cells with recombinant IL-21." (PMID 37628716, 2023). "Tfh cells could couple with B cells to form germinal centers in kidneys, which also could directly promote renal fibrosis by IL-21." (PMID 39080788, 2024). "In the study of this mechanism, we found that recombinant IL-21 could directly promote renal fibrosis and the expression of p65." (PMID 37628716, 2023). "Remarkably, the application of an ICOS-neutralizing antibody effectively prevented the upregulation of TFH cells and expression of its canonical functional mediator IL-21, and also reduced renal TLS formation and renal fibrosis in IRI mice in vivo." (PMID 37628716, 2023). "The expressions of IL-21, formation of TLS, and evaluation of renal fibrosis were measured in mouse kidneys after ischemic-reperfusion injury with or without the utilization of ICOS-neutralizing antibodies to inhibit TFH cell differentiation and function." (PMID 37628716, 2023).
schistosomiasis (3 papers, 2017 to 2023). An infectious disease caused by parasitic trematodes of the genus Schistosoma that colonize human blood vessels and release eggs that can cause granulomatous reactions leading to acute (swimmer's itch or acute schistosomiasis syndrome) or chronic disease. "The data presented here of Luminex analysis displayed markedly correlation between the level of IL-21 or IL-17A in serum and disease severity of schistosomiasis." (PMID 29192177, 2017). "Consistent with previous studies, our co-culture experiment data also suggested that Tfh cells had elevated IgM antibodies production, which, to some extent is dependent on IL-21 in schistosomiasis." (PMID 29192177, 2017). "In conclusion, we proposed that IL-21 would act as a potential immune therapeutic target for anti-fibrosis in schistosomiasis." (PMID 29192177, 2017). "Taken together, Tfh cells are involved in the development of inflammatory pathology by IL-21 driving GC response in schistosomiasis." (PMID 29192177, 2017). "In this study, we demonstrated the key role of IL-21 producing cells to promote liver pathology, particularly in liver fibrogenesis in murine schistosomiasis." (PMID 29192177, 2017). "Several studies have demonstrated that IL-21 is induced at both the mRNA and protein levels during natural infections with several species of schistosomes in humans and in murine models of schistosomiasis, as well as following vaccination with schistosome-derived peptides." (PMID 31867283, 2019). "Thus, it might reveal that Tfh-type cytokine IL-21 contributed to Tfh response in the development of immunopathology in murine schistosomiasis." (PMID 29192177, 2017). "It is likely that the IL-21 promotion of tissue inflammation and immunopathology during schistosomiasis occurs via other signaling pathways independent of the IL-17/STAT3 signaling axis, most likely through STAT1 or STAT5 signaling." (PMID 31867283, 2019). "In addition to providing help to B cells, it is not yet clear whether IL-21 of Tfh cells have other functions, and whether is involved in the development of liver pathology in schistosomiasis." (PMID 29192177, 2017).
Sciatica (3 papers, 2019 to 2021). Pain in the lower back and hip radiating in the distribution of the sciatic nerve. "Previous studies have reported serum inflammatory biomarkers of sciatica, and these include TNF-α, IL-4, IL-6, IL-8, IL-10, IL-17, IL-21, T helper lymphocytes 17, phospholipase A2, C-reactive protein, C-X3-C motif ligand 1, C-C motif ligand 2 and mast cell proteinase-1." (PMID 33535986, 2021).
tetanus (3 papers, 2016 to 2025). A serious infectious disorder that follows wound contamination by the Gram-positive bacterium Clostridium tetani. "A linear mixed-effects model for the repeated measures revealed significant correlations between APRIL and IFN-γ with 12-month tetanus IgG levels and APRIL, BAFF, IL-21, IL-17A, and sCD14 with 12-month pertussis IgG levels." (PMID 37251388, 2023). "The production of 9 cytokines (IFN-γ, TNF-α, IL-2, IL-4, IL-10, IL-17, IL-21, TGF-β, GM-CSF) following in vitro stimulation of PBMCs with tetanus and diphtheria toxoid was analyzed, and was found to be similar in young and elderly adults." (PMID 27602049, 2016).
thymic atrophy (3 papers, 2013 to 2023). "As no mitogen has ever been described for DP thymocytes, we then tested the thymopoiesis-stimulating ability of IL-21 in models of acute and chronic thymic atrophy." (PMID 28615039, 2017). "In wild-type (WT) aged mice displaying naturally induced thymic atrophy, IL-21 enhanced the output of recent thymic emigrants (RTEs), which qualitatively changed the peripheral T cell pool." (PMID 28615039, 2017). "We conclude that IL-21 dramatically accelerates recovery from GC-induced thymic atrophy." (PMID 24023776, 2013). "The goal of this study was to evaluate whether IL-21 could mitigate GC-induced thymic atrophy." (PMID 24023776, 2013). "For instance, IL-21 administration to mice suffering from corticosteroid-induced thymic atrophy led to double-negative (DN) and DP thymocyte expansion, which resulted in accelerated recovery of thymic function." (PMID 28615039, 2017).
thymoma (3 papers, 2016 to 2024). A neoplasm arising from the epithelial cells of the thymus. "Sera from patients with APECED or thymomas and healthy controls were tested for autoantibodies against IL‐6, IL‐1β, IL‐21, IL‐23 (p19 + p40), or TGF‐β3 using LIPS assays that preserve the natural cytokine conformations." (PMID 27957331, 2016). "Luciferase immunoprecipitation (LIPS) was used to screen for autoantibodies to IL‐6, IL‐1β, TGF‐β3, IL‐21, and IL‐23 in patients with APECED or thymoma." (PMID 27957331, 2016).